MAGEA4 (MAGE family member A4)
Diseases named in the same sentence as MAGEA4 in open-access papers (continued):
Sharing a sentence is not in itself a finding about the gene and the disease.
cancer (91 papers, 2002 to 2025). A tumor composed of atypical neoplastic, often pleomorphic cells that invade other tissues. "SSX proteins and SAGE1 (as well as our control antigen, MAGEA4) are cancer testis antigens encoded by genes that are normally only expressed in human germ cells, trophoblast, and certain tumours." (PMID 21706474, 2011). "High expression of MAGEA4 is associated with poor outcomes in cancer." (PMID 41514599, 2025). "In addition, MAGEA4 overexpression has been implicated in numerous cancers and MAGEA4 has long been identified as a promising target for T-cell-based immunotherapy." (PMID 38448672, 2024). "With the use of MAGEA4 in immunotherapeutic techniques, the immune response could be stimulated even further, causing retreating effects of cancer." (PMID 34069064, 2021). "These CT antigens are potential cancer-associated biomarkers, which also play an immunogenic role in tumor-specific cytotoxic T cell response and humoral immune responses as demonstrated by MAGEA4 and SPAG1." (PMID 33287876, 2020). "Cancer-testis antigens have been proposed as targets for immunotherapy approaches and Melanoma-associated antigen 4 (MAGEA4), which was the most highly overexpressed gene in SCCOHT, is currently being investigated as a TCR-engineered T-cell target (NCT03247309)." (PMID 32575483, 2020). "However, the activation of TLS is often associated with error-prone tendencies, and MAGEA4's action may lead to the accumulation of mutations in cancer cell genomes, thereby influencing cancer progression." (PMID 39905312, 2025). "Consistently, in EC samples, we found that MAGEA4 protein is exclusively localized in cancer cells and that its expression inversely correlates with disease outcome in EC." (PMID 41345672, 2025). "By stabilizing RAD18, MAGEA4 facilitates the recruitment of Y-family DNA polymerases, enabling cells to continue replication under DNA damage conditions and thus supporting cancer cell survival." (PMID 39905312, 2025). "Most peptides targeted by TCR-T cells tested in humans so far derive from cancer germline antigens (CGAs), which are highly expressed in cancer and reproductive organs, such as MAGEA4 or CTAG1B, coding for the NY-ESO-1 protein." (PMID 40814001, 2025). "NY-ESO-1, MAGEA4, PRAME, and SSX2 are potential cancer–testis antigens that have been associated with HL in various studies and tested in clinical trials." (PMID 38934093, 2024). "MAGEA4 is a cancer-testis antigen primarily expressed in the testes but aberrantly overexpressed in several cancers." (PMID 38448672, 2024). "Vaccination against MAGEA4 in advanced cancers showed safety and potential immunogenicity based on its expression and HLA class I presence." (PMID 39136024, 2024). "Our data provide unique insights into RAD18-driven PCNA monoubiquitination and the regulation of this process by MAGEA4 in cancers." (PMID 38448672, 2024). "The recruitment of the MAGEA4-Miz1 transcriptional complex on the Cip1/p21 promoter results in the downregulation of Cip1/p21, thus enhancing cancer cell survival." (PMID 38254738, 2024). "A variant of R6BD-based peptide or peptidomimetic with high affinity to the peptide-binding groove (PBG) of MAGEA4 has the potential to be a therapeutic agent in cancers overexpressing MAGEA4 and RAD18." (PMID 38448672, 2024). "Other studies have found that MAGEA4 increases the survival of cancer cells through its interaction with Gankyrin and Miz1, which are transcriptional partners of c-myc." (PMID 38254738, 2024).
cancer (continued). "Our results elucidate how a key cancer antigen is recognized by two novel TCRs and suggest a structural mechanism for preferential binding of the two TCRs to MAGEA4 over MAGEA8." (PMID 37100770, 2023). "Here, we used cryoEM to investigate the structural basis for the recognition of the cancer antigen HLA-A2/MAGEA4 by two TCRs (PN45545 and PN45428) isolated from mice with humanized T-cell immunity." (PMID 37100770, 2023). "We co-cultured tumor associated antigen (TAAs: SSX2, PRAME, MAGEA4, SURVIVIN, and NY-ESO-1) specific CD8+ T cells with partially HLA-matched cancer cells expressing SURVIVIN, MAGE-A3, and MAGE-A4." (PMID 35681750, 2022). "The high stability of MAGEA4-EVs ensures their potential for the development of EV-based anti-cancer applications." (PMID 34069064, 2021). "All these efforts describe MAGEA4 as a highly valued candidate for developing cancer-targeting immunotherapies." (PMID 34069064, 2021). "It has been shown that cancer patients can have a naturally occurring antibody response against MAGEA4." (PMID 34069064, 2021). "We loaded ImmDCs and MaDCs from three donors with a mixture of equal amounts of seven long peptides (25–40 mers) from the known cancer associated antigens PMEL, MAGEA4, MLANA, and CTAG1A (NY-ESO1)." (PMID 32983136, 2020). "It is of note that for cancer patients whose tumor expressing MAGEA4 and MHC I, MAGEA4 vaccines can induce MAGEA4-specific immune responses to activate the CD4+ and CD8+ T cell resulting in the inhibition of tumor cell proliferation." (PMID 33287876, 2020). "The usage of MAGEA4 vaccines have been investigated in several clinical trials and provide new insights for vaccine development in cancer immunotherapy." (PMID 33287876, 2020). "Previous studies have proved that SPAG1 and MAGEA4 participate in the pathogenesis and progression of certain cancers, indicating their potential role as drug targets." (PMID 33287876, 2020). "We show that the cancer/testis antigens MAGEA4 and MAGEA10 are incorporated on the surface of Gag-based particles when transiently expressed together with the MLV Gag protein." (PMID 27403717, 2016). "MAGEA4 is a member of cancer/testis (CT) antigens, which is expressed in malignant cells and in immune-privileged germ-line cells." (PMID 26909861, 2016). "The top hypomethylated gene, MAGEA4, was up-regulated 121-fold, on average, for each of the nine cancer sites it is hypomethylated in." (PMID 25631659, 2015). "MAGEA4 is a cancer/testis antigen and a target for immunotherapy and has been identified to promote growth." (PMID 25631659, 2015). "MAGEA4 represents a potential target for cancer diagnosis and treatment." (PMID 39905312, 2025). "MAGEA4 may promote cancer progression by inhibiting the MAPK signaling pathway or through other mechanisms." (PMID 40244296, 2025). "MAGEA4 is a cancer–testis antigen primarily expressed in the testes." (PMID 40244296, 2025). "Therefore, it is of interest to disrupt this interaction, especially in combination with the genotoxic stress inducing radio/chemo therapy in cancers that are aberrantly overexpressing MAGEA4." (PMID 38448672, 2024). "Aberrant expression of MAGEA4 in cancer cells may encourage PCNA monoubiquitination and the recruitment of error-prone polymerases, even in the absence of DNA damage, through the stabilisation of RAD18." (PMID 38448672, 2024). "MAGEA4 is an interesting candidate for targeted immunotherapy, and recently a MAGEA4‐reactive, HLA‐A2‐restricted T‐cell receptor was engineered, showing effectivity and safety in either CD4 or CD8 preclinical assays, suggesting a clinical strategy for an agnostic treatment of MAGE4 positive cancer." (PMID 37341056, 2023). "Attempts of clinically approved anti-cancer therapeutic approaches involving MAGEA4 have been made." (PMID 34069064, 2021). "The top hypomethylated gene, MAGEA4, is hypomethylated in nine cancer sites." (PMID 25631659, 2015). "XAGE3 and MAGEA4 belong to a family of cancer-testis antigens." (PMID 25742136, 2015).
cancer (continued). "Similarly, the top hypomethylated gene, MAGEA4, is hypomethylated across nine cancers in between 18% and 60% of cases depending on the tissue." (PMID 25631659, 2015). "Interestingly, some overlap exists with autoantibody responses in other cancers, such as MAGEA4 and CEACAM-1, which may reflect shared mechanisms in tumorigenesis." (PMID 39949781, 2025). "Furthermore, the MAGEA4/RAD18 interface represents a potential drug target for cancer therapies." (PMID 38448672, 2024). "Our structural elucidation of the MAGEA4 MHD-RAD18 R6BD complex has provided molecular evidence to clarify confusions caused by the AlphaFold2 modeling and accelerate the development of MAGEA4-RAD18 antagonists to dismantle a key enabling feature of cancer cells." (PMID 38907034, 2024). "Among the most significant genes, a decrease in keratins in HGSIL compared with LGSIL stands out as well as the overexpression of members of the MAGE gene family of cancer/testis antigens in ASCC compared with HGSIL, like MAGEA4, MAGEA3, and MAGEA1." (PMID 39024554, 2024). "Of 90 CTAs validated by RNA sequencing, eight CTAs (DPEP3, EZHIP, MAGEA4, MAGEB2, MAGEC2, PAGE1, PRAME, and TKTL1) were selected for immunohistochemical profiling in cancer tissues from 328 NSCLC patients." (PMID 37341056, 2023). "MAGEA2, MAGEA3, MAGEA4, MAGEA6, and MEGEA12, members of the MAGE family, have been studied for their potential for cancer immunotherapy." (PMID 37655157, 2023). "Other genes overexpressed in Cluster 1 were chemokine and cytokine related genes (CCL15, CCL18, TNF, IL11RA, XCR1), the immune checkpoint protein PD-1 (PDCD1), and cancer-related genes (SSX1 and MAGEA4)." (PMID 33298930, 2020). "The genetic location of miRNA-224 is within a 200 kb region of Xq28 in close proximity to miR-452 within the GABRE gene and is flanked by the MAGEA4 and MAGEA5 cancer antigens." (PMID 24817781, 2014). "MAGEA4-based TCR-T cell therapy and cancer vaccines show clinical potential." (PMID 39905312, 2025). "As a result, seven DEGs correlated with more than 10 TR-DDR genes (r>0.3) in at least 10 cancers were regarded as candidate genes, including COL2A1 (the R ranged from 0.39 to 0.60), MAGEA4 (0.24–0.62), FCRL4 (0.33–0.62), ZIC1 (0.24–0.33), LCN15 (0.20–0.41), PRSS3 (0.24–0.35), CSAG1 (0.31–0.38)." (PMID 36081518, 2022). "Meanwhile, MAGEA4, one of the DEGs between TR-DDR high- and low-score groups, also promotes genome destabilization by contributing to TLS pathway activation, DNA-damage tolerance, and genome maintenance in cancers." (PMID 36081518, 2022). "Previously, we have reported that MAGEA4 is metabolically incorporated into EVs and retrovirus Gag protein-induced virus-like particles (VLP) in cancer cells as well as in cells ectopically expressing the protein where the MAGEA4 protein is exposed on the surface of the vesicles." (PMID 34069064, 2021). "Immature testicular tissue from untreated cancer patients without any evidence of compromised testicular function (NT group) was used to characterize developmental-related changes in spermatogonial marker expression profiles of MAGEA4, UTF1, PCNA, and 5mC." (PMID 31947706, 2020). "Throughout the study, the MLV Gag refers to VLPs obtained by expression of MLV Gag protein without any recombinant cancer antigen, and MART1, TRP1, MAGEA4, MAGEA10 and MCAM mark the VLPs carrying respective cancer antigens." (PMID 27403717, 2016).
tumor (86 papers, 2001 to 2026). "Regarding DFS, patients with MAGEA4-positive tumors exhibited ~ 3-fold higher risk of tumor recurrence (HR = 2.884)." (PMID 41345672, 2025). "MAGEA4 primarily encodes tumor-associated antigens, but here, we observed that MAGEA4 affects various neural signal transduction pathways." (PMID 40244296, 2025). "Melanoma-associated antigen 4 (MAGEA4, also known as MAGE-A4 or MAGE4) is a tumor/testis antigen belonging to the MAGE-A protein family subtype." (PMID 39905312, 2025). "A retrospective evaluation of 908 transitional cell carcinomas of the bladder patients demonstrated strong MAGEA4 staining which was associated with decreased tumor-specific survival (p < 0.0001)." (PMID 38254738, 2024). "Currently, MAGEA4 is regarded as a potential target for tumor treatment, and global pharmaceutical companies have developed several drugs targeting this target, such as Afamitresgene Autoleucel and RG6290." (PMID 41438689, 2026). "Approximately 63% of ESCA patients expressed MAGEA4, contributing to tumor cell lysis when recognized by cytolytic T lymphocytes." (PMID 40083549, 2025). "MAGEA4 expression correlated with disease severity in EC tumor tissue, reinforcing its relevance as both a prognostic marker and immunotherapeutic target." (PMID 41345672, 2025). "Research has shown that TWIST1, as a transcription factor, can upregulate MAGEA4 expression by indirectly binding to the E-box regions of the MAGEA4 promoter sequence, thereby participating in tumor regulation." (PMID 39905312, 2025). "Using a multi-step selection process and analysis of patient tumor tissue, we identify two antigens, MAGEA4 and FAP, as potential targets for an mRNA vaccine." (PMID 41345672, 2025). "Regarding OS, we observed an increased mortality rate and earlier occurrence of tumor-related events (recurrence or death) in MAGEA4-positive EC with longer follow-up (P = 0.03)." (PMID 41345672, 2025). "Twenty-three TAs seemed to be broadly expressed (RPKM > = 1 in more than 75% of the MRTs) while others (e.g., MAGEA4) showed prominent expression in only a subset of the tumor samples." (PMID 40894019, 2025). "MAGEA4 is a member of the Melanoma-Associated Antigen (MAGE) family, characterized by high expression in various tumor tissues but low expression in normal tissues, with the exception of testis and placenta." (PMID 39905312, 2025). "An analysis of MAGEA4 mutant proteins in tumor cells exhibited high structural stability but showed changes in thermal stability and folding that affect tumor growth." (PMID 38254738, 2024). "First, we found multiple MAGE family proteins (e.g., MAGEC2, MAGEB2, MAGEC1, MAGEB6) with a gene expression profile similar to those in clinical trials (MAGEA1, MAGEA4), which have been reported to be tumor specific." (PMID 39515334, 2024). "In this set, we find that BayesTS ranked the well-established CTAs including MAGEA1 and MAGEA4 as the most tumor-specific targets." (PMID 39515334, 2024). "MAGEA4-induced stabilization of RAD18 has been proposed to cause increased tolerance to DNA damage and replicative stress to drive tumour progression." (PMID 38448672, 2024). "Target pairs predicted to independently encode for highly tumor-specific antigens (e.g., MAGEA1, MAGEA4, CLDN18) unsurprisingly resulted in highly tumor-specific antigen pairs as well." (PMID 39515334, 2024). "Among Basal-SCCIS-tumor subgroup-specific genes, MAGEA4 was confirmed to be strongly positive in most SCCIS and invasive cSCC by IHC." (PMID 38099574, 2023). "We found that in MAGEA4+ tumor cells of SCCIS, the stem cell marker COL17A1 and the proliferation marker PCNA were significantly increased compared with the adjacent tissues." (PMID 38099574, 2023). "We then conducted an extensive investigation to evaluate the phenotype, activation status, and cytotoxic potential of these TCR-like CAR-T cells upon exposure to MAGEA4-positive tumor cell lines." (PMID 37894816, 2023).
tumor (continued). "The expression of MAGEA4 in tumor group was significantly higher than that in normal group (p<0.001)." (PMID 38099574, 2023). "Notably, while the MAGEA4 protein was exclusively detected in the tumor cells, FAP was observed in both tumor and surrounding stroma cells." (PMID 41345672, 2025). "At the molecular level, MAGEA4 may play a role in tumor progression by modulating the NF-κB and MMP2 signaling pathways." (PMID 39905312, 2025). "Therefore, understanding the functions and mechanisms of MAGEA4 can provide new insights into how to target MAGEA4 for tumor treatment." (PMID 39905312, 2025). "The combinational approach of co-targeting a tumor cell antigen (MAGEA4) and a CAF antigen (FAP) may enhance and broaden the anti-tumor immune response, potentially overcoming issues of tumor heterogeneity and antigen loss." (PMID 41345672, 2025). "In a clinical trial involving ten patients with recurrent ESCA who received MAGEA4 with TCR-T cell transfer, seven patients exhibited tumor progression within 2 months after treatment." (PMID 40083549, 2025). "MAGEA4 interacts with the RING ubiquitin ligase RAD18 and activates trans-lesion DNA synthesis (TLS), potentially favouring tumour evolution." (PMID 38448672, 2024). "(I) Violin plots showing the expression level of MAGEA4 and ITGA6 in Basal-SCCIS-tumor and Basal-SCCIS-normal subgroups (Wilcoxon test, p_val_adj <0.05)." (PMID 38099574, 2023). "The comparison of the mRNA expression levels of 32 genes of the 21 CTAs between relatively healthy and tumor ovarian tissue showed up-regulation in the expression level of the AKAP3, MAGEA4, PIWIL1, and PRAME genes in tumor samples." (PMID 37835834, 2023). "Considering its potential utility as an indicator for malignancies of SCCIS tumor cells, we performed IF co-localization of COL17A1, PCNA, and MAGEA4 in SCCIS tissues to investigate stemness and proliferative state of tumor cells." (PMID 38099574, 2023). "The epigenetic reactivation of TKTL1, H19, MAGEA2, MAGEA3/6, MAGEA4, MAGEA11, GPR17, GRIN1, and C19ORF28, genes located at diverse chromosomal loci, occurs simultaneously in individual primary tumors from multiple tumor types." (PMID 19305507, 2009). "Significant tumor-specific demethylation was found in MAGEA3 (p<0.005), MAGEA12 (p<0.025), MAGEA4 (p<0.018), MAGEA1 (p<0.001), TKTL1 (p<0.025) and MAGEA5 (p<0.007)." (PMID 19997593, 2009). "Interestingly, RNA expression in tumor tissue was only evident for CEACAM1, MAGEA4, SRC, TPBG, GPA33, and SUB1, with the highest and lowest expression for SRC and MAGEA4, respectively." (PMID 39949781, 2025). "The MAGEA4 expression increased significantly with the following parameters: age (>70 years; P ≤ 0.001); advanced disease stage (FIGO >II; P = 0.001); lymph node involvement (P = 0.026), and tumor grading (P < 0.001)." (PMID 41345672, 2025). "The analysis of the mRNA expression levels of 21 CTAs in healthy and tumor ovarian tissue showed an up-regulation in the expression level of AKAP3, MAGEA4, PIWIL1, and PRAME in tumor samples and a down-regulation in the expression level of CTAG1A, CTAG1B, MAGEC1, and PIWIL2." (PMID 37835834, 2023). "We also identified increased MAGEA4 expression as a potential biomarker of non-responding tumours to vinflunine treatment." (PMID 35053540, 2022). "Currently, the antigens recognized by T cells in HPVnegVSCC are unknown but the majority of primary VSCC express for instance the well-known tumor antigens MAGEA1 and MAGEA4, but it is unknown if these antigens function as target for the VSCC-infiltrating T-cells as this still needs to be studied." (PMID 31481117, 2019).
tumor (continued). "Noticeably, overexpressed NYESO1 (CTAGB1), MUC1, MAGEA3, MAGEA4, or CEA (CEACAM5) antigens did not correlate with TERT improved PFS of patients with high B cell infiltrate, suggesting a selective role of TERT over other common tumor antigens in driving local antitumor immunity." (PMID 36909826, 2023).
adenocarcinoma (3 papers, 2016 to 2024). A common cancer characterized by the presence of malignant glandular cells. "MAGEA4 is known to mediate stabilization of RAD18 through inhibiting its ubiquitin-dependent proteolysis and promoting trans-lesion synthesis in the adenocarcinoma cell line H1299." (PMID 38448672, 2024).